AFP (alpha fetoprotein)
Diseases named in the same sentence as AFP in open-access papers (continued):
Sharing a sentence is not in itself a finding about the gene and the disease.
tumor (continued). "For the younger patients (≤60 years old), the male patients, and the patients with AFP more than 400ng/ml, tumor size more than 5cm, or type III/IV PVTT, the median OS of TACE combined with sorafenib group was longer than that of TACE alone." (PMID 31467872, 2019). "Testis tumor markers were all normal [alpha-fetoprotein (AFP) = 2.87 ng/mL, beta-human chorionic gonadotrophin (β-HCG) < 0.6 mIU/mL]." (PMID 31888599, 2019). "NGGCT include all GCT with some germinal component of malignancy and/or any tumor that secretes alpha-fetoprotein (AFP) or high levels (> 100–200 IU) of ß-human chorionic gonadotropin (ß-HCG)." (PMID 31860688, 2019). "Based on the maximisation of the Youden’s index, the optimal cutoff values for alpha-fetoprotein(AFP) and tumor diameter were 261.6 ng/mL and 3.6 cm, respectively." (PMID 31676847, 2019). "Factors significantly correlating with poor RFS included race other than white, AFP >300, and microvascular invasion on tumor explant." (PMID 31737675, 2019). "PT (P=0.000), album (P=0.031), AFP (0.008), bilobar tumor extent (P=0.004), multiple tumors (P=0.019) and AR (P=0.025) were independent unfavorable prognostic factors for DFS in HCC patients." (PMID 31417639, 2019). "More in details, levels of serum tumor markers such as alpha-fetoprotein (AFP) and carcinoembryonic antigen (CEA) were increased in the group of mice inoculated with Ehrlich carcinoma cells." (PMID 31540249, 2019). "Patients treated with sorafenib were younger, with higher AFP levels, higher proportion of diffuse/infiltrative tumor, more advanced portal vein invasion, and distant metastasis when compared with those that received TACE." (PMID 30845192, 2019). "A novel finding is the inverse association of elevation rates of AFP and bHCG with age in the entire group of GCT patients; i.e., young patients have higher rates of elevated tumour markers than the older ones." (PMID 31275973, 2019). "They showed AFP-positive cell-specific tumor cell suppression that inspired a number of subsequent studies and trials." (PMID 31769427, 2019). "Panels D-F show AFP expression in long term HCC patient of adjacent tissue < 1cm from tumor (D), tissue at operative site (E), and tumor tissue (F)." (PMID 30886700, 2019). "Low p-AMPK expression in HCC was correlated with high-serum α-fetoprotein (AFP) level, incomplete tumor encapsulation, late tumor–node–metastasis (TNM) stage, portal venous invasion, and distant metastasis." (PMID 31083406, 2019). "The preoperative factors that associated with post-LT HCC recurrence included pre-LT TACE, pre-LT AFP, total tumor diameter (cm), the largest tumor diameter (cm) and the number of nodules at all tested cut-off values." (PMID 31752756, 2019). "The anti-tumor potential of cell-free vaccines based on murine DC-derived EVs indirectly loaded with α-fetoprotein (AFP) has been evaluated." (PMID 31680949, 2019). "Correlation analysis revealed that CTC‐297N7.9 expression was significantly related to serum AFP level (P = .007), tumor node metastasis (TNM) stage (P = .011), tumor differentiation (P < .001), and vascular invasion (P = .024)." (PMID 31674731, 2019). "In HCC group, tumor mass, number of lesions, and the level of alpha-fetoprotein (AFP) were recorded." (PMID 30719231, 2019). "The variables AFP (p = 0.002), tumor size (p = 0.040), vascular invasion (p = 0.001), Milan in/out (p = 0.002), and number of nodules (p = 0.003) were also significantly associated with HCC recurrence." (PMID 31141535, 2019). "This study clearly shows and confirms a hepatoprotective role for N. Sativa, P. Ginseng and C. Sempervirens extracts in AFB1 induced HCC rat model evidenced by reduction of liver enzymes (AST and ALT), tumor marker (AFP) and histopathological observations." (PMID 31193706, 2019).
tumor (continued). "CYP2A6 was also associated with worse clinicopathological characteristics including advanced tumor staging, vascular invasion, major portal vein invasion, intrahepatic metastasis, and increased AFP level in our study." (PMID 30148168, 2018). "Univariate analysis showed that cumulative tumor size, tumor number, Edmondson grade, AFP, HBsAg, AST, and PT were prognostic factors for DFS or OS of patients with BCLC stage B HCC." (PMID 30095644, 2018). "AFP, vascular invasion, and tumor size have been confirmed to be significantly correlated with the prognosis of patients with HCC, thus explaining to some extent why the prognosis of HCC patients with elevated LDH levels is worse." (PMID 30687735, 2018). "With respect to tumor markers, AFP was elevated in three of the four combined carcinoma cases and none of MC cases (P = 0.0112); CEA was elevated in three of the four combined carcinoma cases and four of six MC cases (P = 0.7782)." (PMID 29721707, 2018). "Etiology of the chronic liver disease, histopathological grading, tumor nodularity, size, AFP serum levels and time-to-recurrence (TTR) after surgery were tested against LUCAT1, CASC9 and LINC01093 expression." (PMID 30416681, 2018). "Initial work on utilising this knowledge for targeted gene therapy centred on the use of HCC restricted tumour specific promoters, such as that for alpha- fetoprotein (AFP), to drive transgene expression." (PMID 29805757, 2018). "Only tumour size, baseline alpha-fetoprotein level, and the Child-Pugh class had significant prognostic value (HR = 2.51, P < 0.001; HR = 1.76, P < 0.001; HR = 1.56, P = 0.004)." (PMID 29703174, 2018). "Fecal Gal-3 positively correlates with disease severity (advanced TNM stage, higher nuclear grade, and poor tumor tissue differentiation) and progression (presence of lung/liver metastasis or peritoneal carcinomatosis) and systemic biomarkers AFP and CEA." (PMID 29849497, 2018). "Researches demonstrated that when peripheral blood mononuclear cells were cultured in normal umbilical cord blood AFP (nAFP) and tumor derived AFP (tAFP) separately, the phenotype and function of DC cells were altered." (PMID 29805966, 2018). "In multivariable analysis, the independent risk factors comprised tumour number (p = 0.004), pre-transplant alpha-fetoprotein concentration (p < 0.001), presence of microvascular invasion (p = 0.014), and poor tumour differentiation (p = 0.007)." (PMID 29895820, 2018). "We further analyzed the diagnostic performance of each miRNA, AFP levels, the triplex miRNA and the Mir@AFP in distinguishing HCC patients with small tumor sizes from other HBV patient groups." (PMID 29672637, 2018). "After additional 18 months, tumor recurrence was found, including persistent liver metastases, with increasing serum level of AFP of 330,014 ng/ml." (PMID 29933751, 2018). "The SML group was also characterized by features of more advanced tumor progression, such as higher serum AFP level and larger tumor size." (PMID 30041616, 2018). "Some traditional tumor biomarkers such as α-fetoprotein (AFP) had been widely used in clinical practice." (PMID 29717027, 2018). "Regarding tumor markers, serum alpha-fetoprotein (AFP) and carcinoembryonic antigen (CEA) were normal; however, neuron-specific enolase (NSE) was elevated." (PMID 30453967, 2018). "As a result, the recombinant vaccine encoding AFP and HSP70 produced effective AFP-specific T cell response and effectively suppressed the growth of tumor cells, eliciting robust protective immunity against AFP-positive tumors in vivo." (PMID 29805966, 2018). "AFP-modified immune cell vaccine or peptide vaccine has displayed the specific antitumor immunity against AFP-positive tumor cells." (PMID 30355653, 2018). "Rapid tumor growth (10 cm) was detected during last stay in hospital (April 2017), concomitant with a rise of AFP-serum levels to 91 μg/L." (PMID 29510685, 2018).
tumor (continued). "As a comparison with the nomogram, we illustrated the ROC curves using the AJCC tumor stage, tumor size, and AFP in 5-year survival prediction." (PMID 30477582, 2018). "Even in patients who only experienced AFP or radiographic progression, the amplitude of the observed AFP or tumour increase was generally lower." (PMID 29808014, 2018). "Univariate analysis showed that AST levels, albumin levels, PT, AFP levels, tumor size, and treatment methods significantly affected the OS of patients." (PMID 30095644, 2018). "Serum AFP and decarboxy-prothrombin (DCP) levels and tumor size were also significantly associated with the DFS in univariate analysis." (PMID 30274313, 2018). "In patients with localized disease, tumor markers should decline as predicted by their half-lives (AFP < 7 days, ß-HCG < 3 days)." (PMID 30563561, 2018). "In the case presented here, AFP levels were helpful as a serum tumor marker that correlated tightly with the disease burden observed by clinical examination and cross-sectional imaging." (PMID 30208947, 2018). "Meanwhile, serum AFP level, tumor size, and γ‐GT were also determined as independent prognostic factors for both OS and RFS." (PMID 29905011, 2018). "Expression of classic tumor-associated proteins such as β-catenin, EpCAM and CK19 was maintained in acini-like organized tumors on CAM, as was synthesis of AFP, a tumor marker used for monitoring patient response." (PMID 29662633, 2018). "48.5% of all patients showed mainly membranous CA9 expression correlating with younger age, female sex, higher AFP levels, tumor size grading and even survival." (PMID 30011326, 2018). "Immunohistochemistry (IHC) of the primary tumor revealed strong staining for AFP, confirming tumor-derived AFP production." (PMID 30208947, 2018). "Cancer-specific mortalities were comparable between the two groups in patients whose AFP values were lower than 400 mg/mL or whose tumor sizes were smaller than 5 cm in this study." (PMID 29435900, 2018). "The independent predictors of RFS or OS, including α‐fetoprotein (AFP), tumor size, tumor number, microvascular invasion, and NMLR, were incorporated into the two nomograms." (PMID 29533004, 2018). "AFP > 400 ng/ml, large tumor size (> 8 cm), tumor number (> 3), and Protein Induced by Vitamin K Absence II (PIVKA-II) level (> = 200 mAU/ml) has been validated as risk factors associated with the presence of MVI." (PMID 29530006, 2018). "Age, sex, AFP, tumor type, and HBsAg had minimal effects on prognosis, which were not statistically significant (P > .05)." (PMID 29851811, 2018). "Alpha-fetoprotein and IL-6 levels were compared in subgroups and effectiveness of these markers in subgroup 1 (tumor with small diameter) was investigated." (PMID 29963457, 2018). "In particular, patients with dual positivity of postoperative serum MCM6 and AFP should be supplied with more intensive care and close follow-up after they undergo tumor resection." (PMID 29357919, 2018). "AFP >400 ng/mL and non-S3 tumor classification were found to be significantpredictors of overall survival." (PMID 29376136, 2018). "High RBBP5 expression was significantly associated with elevated level of AFP, advanced TNM stage, high Ki-67 expression, larger tumor size, and poor prognosis." (PMID 30533424, 2018). "In the multivariate analysis, and in contrast to the original SNACOR study, we were only able to confirm the predictive value of tumour size, baseline alpha-fetoprotein level, and Child-Pugh class." (PMID 29703174, 2018). "The patient’s disease tracked very closely to serum AFP levels, and the strong expression of AFP on the tumor itself supported the tumor as the primary source." (PMID 30208947, 2018). "The Cox regression analysis used tumour size, tumour number, baseline alpha-fetoprotein level, the Child-Pugh class, and objective radiological response as covariates." (PMID 29703174, 2018).
tumor (continued). "Data from Pawlik’s study suggested that tumor grade, preoperative serum AFP level, number of tumor nodules, and tumor size remained independent predictors of MVI in HCC patients." (PMID 30254101, 2018). "At the time of diagnosis, lactate dehydrogenase (LDH) was 5294 U/L and the tumor markers alpha-fetoprotein (AFP) and beta-human chorionic gonadotrophin (β-HCG) were < 2.5 μg/L and 2526 IU/L, respectively." (PMID 30563561, 2018). "Tumor markers cannot be relied upon to differentiate, as only just over half of patients in one study had elevated Alpha-fetoprotein (AFP) and/or carbohydrate antigen 19.9 (CA19.9)." (PMID 29486800, 2018). "Tumor biomarkers included AFP, CA19–9 and CEA are commonly used biomarkers for cancer prognosis and therapy, while it is not satisfactory in terms of cancer prediction because of the poor prediction efficiency." (PMID 29484118, 2018). "Alpha-fetoprotein and IL-6 were compared in subgroups and the effectiveness of these markers was investigated in subgroup 1 (small-sized tumor)." (PMID 29963457, 2018). "In contrast, lower AFP levels and smaller tumor size, better BCLC stage were independent protective factors for the survival of HBV-related HCC." (PMID 29467672, 2018). "Management of these patients is supported by monitoring tumour markers such as alpha fetoprotein (AFP) and human chorionic gonadotrophin (HCG), which are elevated in patients with metastatic NSGCT in around two-thirds of cases." (PMID 29808086, 2018). "Our score furthermore remained an independent factor against the tumor size and the AFP level in our patient population." (PMID 29435123, 2018). "The results showed that increased USP4 expression was highly correlated with histological differentiation (P = 0.002), tumor size (P = 0.003), tumor number (P = 0.043), vascular invasion (P = 0.003), and serum alpha-fetoprotein (AFP) levels (P = 0.024)." (PMID 29396555, 2018). "Multivariate analyses revealed that the correlations of AFP and tumor stages with disease-free and overall survival." (PMID 29449614, 2018). "For follow-up monitoring to detect disease relapse, blood-based tumor markers alpha-Fetoprotein (AFP), the β-subunit of human chorionic gonadotropin (β-HCG), and Lactate Dehydrogenase (LDH) are commonly measured." (PMID 30321995, 2018). "AFP is a common tumor marker for monitoring postsurgical recurrence and metastasis in patients with positive AFP31." (PMID 29487329, 2018). "Univariate analysis identified the following factors significantly associated with poor OS: LMR < 4.01, AFP ≥ 400 ng/mL, BCLC stage B or C, multiple tumors, tumor size ≥ 5 cm, incomplete tumor capsule, AST ≥ 80 U/L, NLR ≥ 2.78 and PLR ≥ 99.5." (PMID 29416061, 2018). "We have assessed concentration of pro- and anti-inflammatory cytokines, as well as Gal-3, and tumor markers (AFP, CEA, and CA19-9) in serum and feces liquid fraction." (PMID 29849497, 2018). "Although previous studies have demonstrated that AFP levels, tumor size, and BCLC stage were independent predictors for the survival of HCC." (PMID 29467672, 2018). "Contrast-enhanced CT, blood tests, liver and thyroid function tests, and measurements of tumor marker levels (e.g., AFP, NSE, and VMA) were performed in the NICU." (PMID 29291724, 2018). "We observed identical histologies in PDX-derived tumor tissues and the original patients' tumor samples using H&E staining, which was accompanied by the strong expression of AFP, a marker highly expressed in HCC." (PMID 29706843, 2018). "Palliative chemotherapy led to tumor shrinkage and a concurrent decrease in the serum alpha-fetoprotein level." (PMID 29992073, 2018). "The median age, BMI, tumor weight, serum AFP, ALBadjust, creatinineadjust, PLT, and PT of patients were 62, 25.1, 240, 13, −0.05, −0.05, 211, and 1.1, respectively, and the deaths occurred in the current cohort were 74 (45.1%)." (PMID 30378276, 2018).
tumor (continued). "The reduction in tumor load was confirmed by the measurements of mRNA levels of alpha-fetoprotein (AFP), a HCC biomarker, which was significantly reduced in SphK1−/− compared to WT mice." (PMID 29643998, 2018). "Testicular tumour markers were unremarkable: alpha-fetoprotein (AFP), beta human chorionic gonadotropin (hCG), and lactate dehydrogenase (LDH)." (PMID 31447972, 2018). "Intriguingly, lncPARP1 up-regulation was markedly associated with elder age, higher level of serum α-fetoprotein (AFP), larger tumor size, and recurrence." (PMID 29776974, 2018). "And MVI-positive group had poor tumor status including poorer tumor differentiation, higher proportion of satellite lesions, multiple HCCs, higher rate of patient with AFP greater than 400 ng/ml, and larger tumor size." (PMID 29530006, 2018). "In this study, the HAP score was a little bit high (albumin, 41.1 g/dl; bilirubin 17.8 μmol/l; tumor size, 8.6 cm; and 47% of cases with AFP > 400 ng/ml)." (PMID 29879928, 2018). "Univariate analysis showed that GSTP1 expression, as well as AFP, tumor number, tumor size, PVTT, TNM stage, and Edmondson-Steiner grade were related to OS and DFS in HCC patients." (PMID 29507666, 2018). "In detail, 113 patients were hepatitis B virus surface antigen (HBsAg)-positive, 74 patients had higher serum AFP concentration, 63 patients had maximal diameter of tumor ≤5 cm and 97 patients had grade I or II tumors." (PMID 30537941, 2018). "One study compared methylation levels of the AFP gene in tumor versus normal liver tissue and found that tumor had lower AFP methylation levels." (PMID 30577683, 2018). "In summary, we present a case of deep response to anti-PD-1 therapy with a tumor that strongly expressed AFP, which served as a reliable tumor marker and possibly as immunogenic antigen." (PMID 30208947, 2018). "The three main poor prognosis factors in patients with HCC are the regular increase of AFP, an AFP level of over 1000 ng/mL and the invasion of the portal vein by the tumour." (PMID 30064414, 2018). "A comparison with traditional serum tumor markers showed a sensitivity of 98% for miR-371a-3p and miR-367 levels compared to a sensitivity of 50% for AFP and β-HCG." (PMID 30321995, 2018). "Reduced CBS expression was significantly correlated with the poor clinic pathological parameters including tumor stage, Edmondson grade, alpha-fetoprotein (AFP) level, and overall survival." (PMID 30050925, 2018). "Results revealed that high ANLN expression had a significant association with a large tumor size (P = 0.008), a high TNM stage (P < 0.001), a high AFP level (P = 0.002), a poor differentiation (P = 0.003) and death events (P = 0.004)." (PMID 30103211, 2018). "The elevation of serum tumor markers, such as CA-125 and AFP in the current case has been found in previous studies." (PMID 29933751, 2018). "Namely, the serum iron levels <15.1 μmol/l was a significant risk factor for HBV- related HCC development with a hazard ratio of 2.28 (95%CI, 1.82–2.87; P < 0.001) together with higher AFP levels, larger tumor size and worse BCLC stages." (PMID 29467672, 2018). "LMR < 4.01, AFP ≥ 400 ng/mL, B multiple tumors, tumor size ≥ 5 cm, incomplete tumor capsule and NLR ≥ 2.78 were also found to be significantly associated with poor DFS." (PMID 29416061, 2018). "The results of the univariate Cox hazards analysis revealed that the AJCC tumor pathological stage, tumor size, tumor metastasis, and AFP level were related to 5-year survival." (PMID 30477582, 2018). "The tumor was found to be an AFP-producing adenocarcinoma on further immunohistopathological examination." (PMID 30191347, 2018). "More patients in the ramucirumab arm experienced tumour shrinkage and AFP response compared with placebo." (PMID 29808014, 2018). "In contrast, lower AFP levels, smaller tumor size, and better BCLC stage were independently protective factors for the survival of HBV- related HCC." (PMID 29467672, 2018).